TLR5 (toll like receptor 5)
Diseases named in the same sentence as TLR5 in open-access papers (continued):
Sharing a sentence is not in itself a finding about the gene and the disease.
E. coli infection (6 papers, 2015 to 2023). "Low expression of TLR5 helps to inhibit immune responses, reduce cell damage, and promote resistance to Escherichia coli infection in weaned piglets." (PMID 36499043, 2022). "The reason being, in response to pathogenic Escherichia coli infection, during the contact process between bacterial flagellin and Toll-like receptor (TLR) 4 and TLR5 in gut epithelial cells, PE is an essential stimulus of the Toll-like receptor signaling pathway to induce inflammation further." (PMID 34608242, 2021). "Moreover, in response to uropathogenic Escherichia coli infection, TLR4 and TLR5 together trigger epididymal innate immune responses." (PMID 37152990, 2023). "Indeed, the E. coli infection modifies TLR5 distribution and increases its presence on the cell surface through EPEC flagellum, translocation of effectors and intimate adherence; in turn, the modulation of TLR5 leads the intimate adherence that alters the proinflammatory response." (PMID 36552020, 2022).
hepatocellular carcinoma (6 papers, 2020 to 2025). A malignant tumor that arises from hepatocytes. "Interestingly, Clostridia species are highly present in mice which develop an HCC and a depletion in butyrate-producing bacteria has been reported to reduce the incidence of the hepatocellular carcinoma in TLR5 knockout mice." (PMID 34489956, 2021).
triple-negative breast carcinoma (6 papers, 2019 to 2025). An invasive breast carcinoma which is negative for expression of estrogen receptor (ER), progesterone receptor (PR), and human epidermal growth factor receptor 2 (HER2). "Downregulation of TLR5 has been shown to promote proliferation, metastasis, and epithelial-to-mesenchymal transition (EMT) in triple-negative breast cancer (TNBC), whereas high TLR5 expression is linked to diminished metastatic potential and favorable clinical outcomes." (PMID 40497049, 2025). "For example, downregulation of TLR5 in triple-negative breast cancer (TNBC) increased tumor invasiveness and epithelial–mesenchymal transition (EMT) expression and promoted TNBC metastasis; TLR9 agonist CpG oligonucleotide was widely shown to have an anti-tumor effect by stimulating local immunity." (PMID 36344505, 2022). "Using two triple-negative breast cancer (TNBC) cell lines MDA-MB-468 and MDA-MB-231, we show that FnEDA and FnIII-1c induce the pro-tumorigenic cytokine, IL-8, by serving as agonists for TLR5 and TLR2, the canonical receptors for bacterial flagellin and lipoprotein, respectively." (PMID 35805158, 2022).
Allergy (5 papers, 2012 to 2020). An allergy is an immune response or reaction to substances that are usually not harmful. "One study investigating a potential role for TLR5 in allergy used flagellin to stimulate cord blood mononuclear cells." (PMID 33281825, 2020). "Recent studies of TLR5 activation as a strategy for treating allergic disease have used a TLR5 fusion protein conjugated with different allergens to explore the impact on T cell phenotype and downregulation of the Th2 response and the durability of the effect." (PMID 33281825, 2020). "TLR5-dependent IL-10 secretion has also been described as part of the response to a flagellin fusion protein studied to prevent allergy; our findings are consistent with this observation." (PMID 31776239, 2019). "In several experimental allergy models, such conjugates, for example, incorporating TLR5-, TLR7/8-, and TLR9-ligands, have been described to have beneficial immune-modulating properties by promoting Th1- and appropriate regulatory responses." (PMID 27340679, 2016). "Previous studies investigating the effects of adjuvant : allergen fusion proteins, including TLR5-, TLR7-, and TLR9-ligands, on the modulation of allergen-specific immune responses demonstrated the potential for such conjugate vaccines to improve allergy treatment." (PMID 27340679, 2016). "Another study demonstrated increased production of tumor necrosis factor-alpha and interleukin-1 in cord blood mononuclear cells upon TLR2, TLR4, and TLR5 activation in newborns who later develop allergic diseases, suggesting a link between heightened perinatal TLR response and allergy development." (PMID 21912563, 2012).
Alzheimer disease (5 papers, 2020 to 2025). A progressive, neurodegenerative disease characterized by loss of function and death of nerve cells in several areas of the brain leading to loss of cognitive function such as memory and language. "Furthermore, recent studies identified TLR5 as being involved in different CNS disorders lacking a primarily pathogen-associated cause, including Alzheimer’s disease (AD), neuropathic pain, and cerebral ischemia." (PMID 32912327, 2020). "In pathological conditions, amyloid-β (Aβ) and tau (key players in Alzheimer’s’ disease (AD)) induce TLR4 activation, while α-synuclein (a key player in Parkinson’s disease (PD)) induces TLR2 and TLR5 activation." (PMID 41280719, 2025). "Upregulation of TLRs expression was observed in a variety of chronic neurodegenerative diseases, such as Alzheimer’s disease (TLR2 and TLR4), multiple sclerosis (TLR 1-8), and Parkinson’s disease (TLR2 and TLR5)." (PMID 35740099, 2022). "While TLR2, TLR4, TLR5 and TLR10 might be involved in the pathogenesis of systemic sclerosis, TLR activation can have both destructive and protective effects on Alzheimer ́s disease (AD)." (PMID 33499143, 2021).
bacteremia (5 papers, 2010 to 2024). "Higher expression levels of TLR5 on monocytes were associated with increased mortality, documented bacteremia, and higher Sequential Organ Failure Assessment scores of the septic patients." (PMID 30944018, 2019). "Higher TLR5 expression levels were associated with documented bacteremia and higher SOFA scores of the septic patients on the day of study enrollment." (PMID 30944018, 2019). "We have previously reported associations of TLR1 single nucleotide missense variant rs76600635 with mortality and of TLR5 nonsense variant rs5744168 with both bacteremia and mortality in single-center studies of patients with melioidosis in northeastern Thailand." (PMID 38507807, 2024). "Therefore, in this study, we take advantage of a large prospective, multicenter observational study that recruited melioidosis patients hospitalized in northeastern Thailand to test the associations of TLR1 variant rs76600635 and TLR5 variant rs5744168 with bacteremia and mortality in melioidosis." (PMID 38507807, 2024). "Associations were found between the CC genotype of IL6 SNP rs1800795 and occurrence of bacteremia and between TLR5 SNP rs5744168 and protection from UTI." (PMID 25807366, 2015). "We conclude that in a large multicenter cohort of patients hospitalized with melioidosis in northeastern Thailand, neither TLR1 missense variant rs76600635 nor TLR5 nonsense variant rs5744168 is associated with bacteremia or mortality." (PMID 38507807, 2024). "In addition we identified several modest genetic associations, especially between TLR5 SNP rs5744168 and UTI and between IL6 SNP rs1800795 and occurrence of bacteremia." (PMID 25807366, 2015). "Our observation that higher expression levels of TLR5 on monocytes were associated with poorer outcomes and an increase in the incidence of bacteremia of septic patients suggests that monocyte TLR5 expression might be a potential indicator of immune dysfunction and mortality." (PMID 30944018, 2019).
cervical cancer (5 papers, 2017 to 2024). A primary or metastatic malignant neoplasm involving the cervix. "TLR-5 was associated with an increased presence of bacterial flagella that would be responsible for the migration and proliferation of cancer cells in cervical cancer and non-small cell lung cancer." (PMID 38067244, 2023). "In addition, the TLR9, TLR10, and TLR5 cascades were associated with the DE genes in our study, and they were similarly dysregulated in HPV infection and cervical cancer progression." (PMID 32151264, 2020). "However, evidence suggests that HPV may influence TLR4 and TLR5 in cervical cancer development." (PMID 39273663, 2024). "They observed increased mRNA expression of TLR5 and TLR9 in epithelial cells with severe SILs and cervical cancer, while in healthy cells or those with mild SIL, the mRNA expression of TLR5 and TLR9 was minimal or absent." (PMID 39273663, 2024). "Studies also found that TLRs, especially TLR4, TLR5 and TLR9, are closely related to HPV infection and cervical cancer." (PMID 29263932, 2017).
HIV-1 infection (5 papers, 2009 to 2024). The type species of lentivirus and the etiologic agent of acquired immunodeficiency syndrome (AIDS). "However, despite these findings, it is unclear about the mechanism(s) by which flagellin—TLR5 interactions interfere with HIV-1 infection/replication." (PMID 39066226, 2024). "Given the important role of flagellin as a vaccine adjuvant in TLR5 activation-mediated immune regulation and in HIV-1 infection of macrophages, we examined the impact of the flagellins from different bacteria on HIV-1 infection of primary human macrophages and the mechanism associated with them." (PMID 39066226, 2024). "The toll-like receptor (TLR) family member 5 (TLR5, in M4.2) is an important innate pathogen recognition receptor that is involved in the recognition of bacterial flagellin, and is also reported to trigger reactivation of latent HIV-1 infection and activate virus gene expression in T cells." (PMID 23658707, 2013). "We chose TLR5 and TLR9 ligands to investigate the effects of their engagement on HIV-1 infection and the mechanisms for this phenomenon, because of their opposite effects on HIV-1 irrespectively of its coreceptor specificity." (PMID 20862220, 2010).
leptospirosis (5 papers, 2014 to 2024). A contagious bacterial infection caused by spirochetes of the genus Leptospira. "This was further supported by the findings that the course of leptospirosis is unaltered in TLR5-/- mice." (PMID 35937697, 2022). "Human/bovine TLR5 and human NOD1 might therefore play a specific role during acute leptospirosis in a susceptible host, considering that they can sense released agonists upon bacterial degradation." (PMID 35937697, 2022). "To study the potential involvement of the TLR5 receptor in the host defense against leptospires, we used a murine model of leptospirosis and compared the susceptibility of C57BL6/J (WT) mice versus tlr5 knock-out (TLR5ko) mice after intraperitoneal infection with a sublethal dose of 107L." (PMID 32849665, 2020). "Besides the role of TLR2 in response to leptospirosis, the involvement of TLR4 and TLR5 was identified in in-vitro and in-vivo studies." (PMID 39729468, 2024). "Altogether these results suggest that the presence of TLR5 does not play a major role in the murine defense at the acute phase of experimental leptospirosis." (PMID 32849665, 2020). "Aside from TLR2 and TLR4, other TLRs that have not yet been studied in the context of leptospirosis, such as TLR5 that senses flagellin, and TLR9, the receptor of bacterial DNA, could in theory be involved in the murine defense against L. interrogans." (PMID 24498450, 2014).
liver fibrosis (5 papers, 2017 to 2025). "In contrast, in another study on tlr-5-deficient mice, the role of tlr-5 in CCl4-induced liver fibrosis was investigated." (PMID 35165344, 2022). "Intraperitoneal flagellin injections in mouse models of hepatic fibrosis significantly reduced the severity of fibrosis through TLR5 and type 1 interferon responses." (PMID 39235984, 2025). "TLR5 knockout (TLR5 KO) mice displayed an increased propensity for liver fibrosis and lipid accumulation under the MCD diet, exacerbating liver pathology." (PMID 39957532, 2025). "Overall, the findings regarding the exact role of tlr-5 in the prevention or induction of liver fibrosis are contradictory, considering the limitations or different models used to induce liver damage." (PMID 35165344, 2022). "A recent study demonstrated the involvement of TLR5-mediated MAPK signaling in CCL4-induced liver fibrosis development, as manifested by enhanced collagen accumulation and inflammatory infiltration in HSCs." (PMID 28472150, 2017). "In addition, targeting hepatic TLR5 signaling to treat liver fibrosis using postbiotics like flagellin has also been shown." (PMID 39235984, 2025). "Also, in tlr-5 knockout mice, CCl4-induced hepatic fibrosis was reduced by inhibiting smooth muscle alpha-actin (α-SMA) and collagen expression." (PMID 35165344, 2022). "Therefore, modulation of TLR5 signaling might be a promising target toward developing antifibrotic therapeutics for the improvement of liver fibrosis." (PMID 39201329, 2024).
Lyme disease (5 papers, 2013 to 2025). Lyme disease (named after the towns in the USA where the disease was first identified) is a bacterial infection caused by Borrelia burgdorferi. "In our initial investigation of TLR1, TLR2, and TLR5 variants in Lyme disease, we found that patients with post-infectious LA had a greater frequency of TLR1-1805GG (62%) compared to patients with antibiotic-responsive LA (47%)." (PMID 41333458, 2025). "Among other TLRs, TLR5 in primate microglia, and also astrocytes, triggers the production of proinflammatory molecules in response to Borrelia burgdorferi, thereby possibly contributing to Lyme neuroborreliosis." (PMID 32912327, 2020).
lymphoma (5 papers, 2014 to 2022). A malignant (clonal) proliferation of B- lymphocytes or T- lymphocytes which involves the lymph nodes, bone marrow and/or extranodal sites. "Higher levels of TLR3 and TLR5 were associated with a cluster of six sensitive and two resistant lymphomas." (PMID 34913612, 2022). "TLR expression was highly variable among lymphoma subtypes; for example, TLR5 showed lower expression in follicular lymphoma, and TLR2 was overexpressed in both diffuse large B-cell lymphoma and peripheral T-cell lymphoma." (PMID 35715478, 2022). "The identification of microbial and/or endogenous ligands for TLR1/2 or TLR5 may provide new therapeutic targets to be exploited to counteract the tumor promoting effects of lymphoma microenvironment." (PMID 27123851, 2016). "Primary lymphoma cells from a MCL case showed detectable levels of TLR2 and, more markedly, of TLR5 as compared to those of purified normal B lymphocytes." (PMID 27123851, 2016). "We examined the effect of CBLB502 on tumor immunity using two syngeneic lymphoma models, both of which do not express TLR5, and thus do not directly respond to CBLB502." (PMID 24454895, 2014). "To this end, we utilized two syngeneic lymphoma models that do not directly respond to CBLB502, since flagellin can directly interact with TLR5-expressing tumors and subsequently promote tumor growth or inhibit tumor growth depending on the tumor model." (PMID 24454895, 2014).
gastritis (4 papers, 2014 to 2025). Inflammation of the stomach. "These complementary approaches then suggested active gastritis, which correlates with TLR5, and phosphorylated S6K1, a substrate of mTOR, as the most practical surrogate markers for responses to H. pylori eradication therapy." (PMID 34913612, 2022). "In the third step, we showed active gastritis and phosphorylated S6K1 as surrogate markers for TLR5 and mTOR, respectively." (PMID 34913612, 2022). "While TLR2, TLR4, TLR5, and TLR9 appear to be important for H. pylori recognition, their role in the evolution of gastritis to more advanced lesions remains unclear." (PMID 25101079, 2014). "Using confocal microscopy, TLR4, TLR5 and TLR9 have been observed in the antrum and corpus of the stomach samples from patients with H. pylori-related gastritis and with non-inflamed gastric mucosa." (PMID 40362298, 2025).
glioma (4 papers, 2020 to 2023). A benign or malignant brain and spinal cord tumor that arises from glial cells (astrocytes, oligodendrocytes, ependymal cells). "In particular, we focused on the molecular mechanisms and signaling pathway promoting microglial chemotaxis, phagocytosis, cytokine production, and interaction with glioma cells as a consequence of TLR5 activation in these cells." (PMID 32912327, 2020). "RT-qPCR showed that TLR5, 7, 8, and 9 were consistently upregulated in the two stocks of human primary glioma cells after ADV infection." (PMID 32843056, 2020). "Using this model, we explored whether TLR5 activation plays a role in glioma growth in brain slices derived from WT and Tlr5−/− mice." (PMID 32912327, 2020). "In glioma, elevated TLR1, TLR2, TLR4, TLR5, TLR6, and TLR9 expressions were observed in tumor cell lines and tissues compared with non-neoplastic brain tissues, particularly in the mesenchymal subtype of GBM." (PMID 34715891, 2021). "Up to date, TLR2, TLR3, TLR4, TLR7, and TLR9 have been intensely studied in glioma, while less or missing information is available regarding the mechanisms of TLR1/TLR6 (dimerizes with TLR2), TLR5, TLR8 (dimerizes with TLR7), and particularly TLR10." (PMID 34715891, 2021). "Activation or depletion of microglial TLR5, which specifically recognizes flagellin and usually associate with neurodegenerative disease, had no impact on the growth of murine GL261 gliomas." (PMID 34715891, 2021). "In our experimental glioma set-up, however, neither TLR5 stimulation by flagellin nor deletion of TLR5 signaling as assessed by analyzing Tlr5−/− mice, had an impact on glioma growth." (PMID 32912327, 2020). "Activation of TLR5 in microglia and mediates the release of multiple inflammatory molecules causing inflammatory neuronal damage in the CNS, but in contrast to TLR 2/3/4/7/9, TLR5 is not involved in microglia-glioma interactions." (PMID 37700840, 2023). "Furthermore, while TLR5 activation does not affect tumor growth in an ex vivo GL261 glioma mouse model, it triggers microglial accumulation and neuronal apoptosis in the cerebral cortex in vivo." (PMID 32912327, 2020). "The experiments using the GL261 glioma mouse model were prompted by our previous results on the promotion of tumor growth involving TLR2, TLR4, and TLR7 signaling, and were driven by the assumption that TLR5 might detect host-derived molecules." (PMID 32912327, 2020). "The impact of TLR3, TLR5, TLR7, TLR8, and TLR10 signaling in glioma development is not fully elucidated." (PMID 34715891, 2021).
ileitis (4 papers, 2010 to 2024). "In a CD-like ileitis mouse model, TLR5 activation increased epithelial permeability and reduced tight junction protein expression." (PMID 39165421, 2024). "X-linked inhibitor of apoptosis protein (XIAP)-mediated resilience of TLR5 signaling in the TLR5-expressing Paneth cells and the intestinal DCs enabled them to maintain tissue integrity and microbiota homeostasis during ileitis." (PMID 37191444, 2023).
immune deficiency (4 papers, 2017 to 2024). "There has also been a report of activation of NLRC4 resulting in dampening of Toll-like receptor 5–induced antibody response to flagella, raising the possibility of an associated immunodeficiency." (PMID 29778503, 2018). "Furthermore this immunodeficiency impacted similarly on the TLR5 signalling pathway of the vaginal tissues." (PMID 28887442, 2017).
Legionella infection (4 papers, 2017 to 2022). "This supports the notion that recognition of FlaA and subsequent TLR5-mediated immune response plays an important role for pathogen clearance during human Legionella infections." (PMID 35625552, 2022).